COMP (cartilage oligomeric matrix protein)
Diseases named in the same sentence as COMP in open-access papers (continued):
Sharing a sentence is not in itself a finding about the gene and the disease.
osteoarthritis (continued). "By screening potential causal genes for osteoarthritis, we identified a heterozygous missense mutation of COMP (c.1358C>T, p.Asn453Ser), absent from genome databases, located on a highly conserved residue and predicted to be deleterious." (PMID 34680093, 2021). "COMP (a member of the thrombospondin gene family that is involved in human limb development, chondrocyte phenotype maintenance and chondrogenic induction of stem cells and is upregulated in osteoarthritis) expression was also upregulated." (PMID 34632361, 2021). "In fact, ADAMTS-12 participation in arthritic processes has been mainly related to its ability to degrade COMP because fragments generated following its cleavage were found in diseased cartilage, synovial fluid and in serum of patients with knee injuries, osteoarthritis and rheumatoid arthritis." (PMID 33996918, 2021). "The results of this study show that COMP and PG-AG may be sensitive markers differentiating patients with osteoarthritis from psoriatic arthritis." (PMID 33396347, 2020). "Expression of COMP gene mRNA was upregulated in osteoarthritis cases." (PMID 31665048, 2019). "Future studies will aim to determine whether high levels of COMP in the prostate or the serum and/or whether the severity of osteoarthritis impacts its relationship with prostate cancer." (PMID 31413818, 2019). "Also, patients with osteoarthritis expressed increased COMP levels in the prostate and most likely in distant lymphatic nodes." (PMID 31413818, 2019). "Our secondary aim was to determine whether a diagnosis of osteoarthritis correlated with upregulation of tumor markers associated with angiogenesis (CD31), proliferation (Ki-67) and the presence of COMP." (PMID 31413818, 2019). "The objective of this study was to determine whether osteoarthritis had an impact on outcomes of prostate cancer including death, local recurrence and/or metastasis and to determine whether cartilage oligomeric matrix protein was involved." (PMID 31413818, 2019). "Disulfide bound complexes of lubricin and cartilage oligomeric matrix protein (COMP) have recently been identified in arthritic synovial fluid suggesting they may be lost from the cartilage surface in osteoarthritis and inflammatory arthritis." (PMID 29030641, 2017). "COMP-deficient mice in B10.Q background have no microscopic or macroscopic sign of osteoarthritis or other pathologies in a large number of normal young and old (more than 1 year) mice (data not shown)." (PMID 19014566, 2008). "The absence of CHOP reduced ER stress and disrupted the pathological processes associated with mutant COMP, providing a potential mechanism for these therapeutic effects, consistent with other studies showing decreased osteoarthritis damage in mice lacking CHOP." (PMID 39795874, 2024). "Furthermore, serum markers of osteoarthritis, including COMP and HA, were also evaluated." (PMID 38069100, 2023). "Furthermore, an animal experiment on a rat model showed that exposure to particulate matter affects osteocalcin, cartilage oligomeric matrix protein, and N-telopeptides of type I collagen, resulting in decreased bone density, cartilage wear and structural damage, and development of osteoarthritis." (PMID 34574569, 2021). "Studies on osteoarthritis in both humans and horses indicate that COMP may be a good marker for certain joint diseases, while the analysis of fragmentation patterns in joint synovial fluid suggested that COMP fragments were the most sensitive indicators of disease." (PMID 32245107, 2020). "Moreover, the reduction of COMP secretion also affects the assembly of collagen fibers, leading to a decrease in articular cartilage mechanical strength and the occurrence of early-onset osteoarthritis." (PMID 32460719, 2020).
osteoarthritis (continued). "Joint arthroplasty removes the areas of the joint involved in osteoarthritis and could thereby lead to decreased systemic levels of COMP, which in turn would reduce COMP-mediated promotion of cancer proliferation compared to osteoarthritis patients who did not undergo arthroplasty." (PMID 31413818, 2019). "Therefore, it has been postulated that the COMP response to loading may provide a measure of the health of joint cartilage and help identify abnormalities or disease such as osteoarthritis." (PMID 31650307, 2019). "However, these procedures do not guarantee prevention of early onset osteoarthritis of the knee because the cartilage matrix defect originates from mutations of either MATN3 or COMP." (PMID 24629099, 2014). "COMP can be measured in patients serum samples by an IVD approved ELISA and is used to assess cartilage turnover in patients with osteoarthritis." (PMID 38563861, 2024). "Core binding factor-β was highly expressed in the osteoarthritis cartilage (p < 0.001), and MMP-13, IL-1β, COMP and YKL-40 expression were greater than found in normal cartilage (p < 0.001)." (PMID 33573620, 2021). "Several studies have focused on CTX-II and COMP in osteoarthritis and rheumatoid arthritis, and only a few have reported the specific correlation between CTX-II and COMP." (PMID 34395611, 2021). "Cartilage tissues, from healthy subjects and patients with osteoarthritis, were collected for histology and expression of Core binding factor-β, MMP-13, IL-1β, COMP, and YKL-40." (PMID 33573620, 2021). "These cases are known as EDM1 (or COMP-MED), and are characterized by mild short stature, premature osteoarthritis of load-bearing joints, and abnormalities of the epiphyses of hands, long bones, and hips." (PMID 32460719, 2020). "The products of cartilage breakdown, such as COMP and hyaluronic acid, were also found to be higher in MIA-treated rats compared to the sham group, comparable to observation in previous MIA osteoarthritis models." (PMID 31412648, 2019). "Of the biomarkers investigated, it seems that COMP, hyaluronan, and urinary CTX-11 have had the most consistent utility for the incidence and progression of osteoarthritis." (PMID 31650307, 2019). "A recent systematic review assessing COMP, CTX-11, and MMP-3 in knee and hip osteoarthritis patients found that COMP and urinary CTX-11 can distinguish osteoarthritis patients from healthy, with COMP effectively able to predict osteoarthritis progression." (PMID 31650307, 2019). "The levels of serum COMP and urine CTX-11 in patients with osteoarthritis of the knee in response to muscle strength training in combination with treatment with glucosamine, ibuprofen or placebo has also been investigated." (PMID 31650307, 2019). "COMP also functions as an ECM stabilizer, and is upregulated with joint loading during exercise and secreted to the serum in patients with osteoarthritis." (PMID 31413818, 2019). "The area under the curve (AUC) of COMP, CS846, and combined biomarkers in the evaluation and diagnosis of osteoarthritis was analyzed by ROC curve analysis." (PMID 30208927, 2018). "In addition, the levels of COMP and TNF-α varied significantly among groups A, B, and C (p < 0.01 or P < 0.05), which suggested that the injection with increasing amounts of MIA caused knee osteoarthritis of increasing severity (light, mild, and heavy osteoarthritis)." (PMID 30105061, 2018). "Serum cartilage oligomeric matrix proteins (COMP), bone alkaline phosphatase (bALP), osteocalcin, PINP, synovial fluid hyaluronic acid and MMP‐1 levels at 0 h, 15, 30 and 60 days in dogs with osteoarthritis treated with meloxicam and pentoxifylline (Mean ± SD)." (PMID 40434930, 2025). "Notably, CS significantly reduced the levels of extracellular matrix degradation markers COMP and CTX-II in a rat model of osteoarthritis." (PMID 39859238, 2025).
osteoarthritis (continued). "Furthermore, it was used to detect cartilage oligomeric matrix protein (COMP) in synovial fluid, where an elevated concentration in an osteoarthritis sample versus a control aligned with its role as a cartilage catabolism marker." (PMID 41516471, 2025). "Correlation between urinary C-telopeptide of type II collagen (CTX-II), serum cartilage oligomeric matrix protein (COMP), and plasma 25(OH)D with visual analogue scale (VAS) pain and knee injury and osteoarthritis outcome score (KOOS) domain scores at baseline (n = 49)." (PMID 36544504, 2022). "Some studies have shown that CTX-II and COMP are potential molecular markers for joint degenerative diseases as detected by serology; however, the correlation between CTX-II and COMP concentrations and IVDD is yet unknown." (PMID 34395611, 2021). "The noncollagen protein COMP, the biomarker in osteoarthritis, mainly isolates from cartilage and contributes to maintaining the stability of collagen II in cartilage." (PMID 33014527, 2020). "The observation of increased COMP expression in a lymph node of an osteoarthritis patient of twice the amount of that in a patient without osteoarthritis is promising, novel and the first of its kind in the literature." (PMID 31413818, 2019). "The IHC analysis revealed that COMP levels were significantly higher among biopsies of patients with osteoarthritis, compared to patients without osteoarthritis." (PMID 31413818, 2019). "However, the two processes are closely related, as suggested by the concomitant increase in the levels of cartilage oligomeric matrix protein (COMP) and bone sialoprotein (BSP) in people with early osteoarthritis." (PMID 24653755, 2014). "ADMED can be due to; COMP (cartilage oligomeric matrix protein), COL9A1-COL9A3 (collagen type IX alpha 1–3 chain) or MATN3 (matrilin 3) and presents in childhood with joint pain, exercise-induced fatigue, restricted mobility, short stature, and early-onset osteoarthritis." (PMID 34092239, 2021). "However, the effects of COMP on prostate cancer progression in patients with osteoarthritis have not been studied and could present a novel therapeutic approach to prostate cancer treatment." (PMID 31413818, 2019). "Urinary type II collagen C-telopeptide fragment (CTX-II) and serum cartilage oligomeric matrix protein (COMP) are two possible biomarkers of cartilage ageing but they have not been shown to be reliable markers of collagen ageing per se, independent of osteoarthritis." (PMID 30202858, 2018). "Furthermore, it has been found to degrade cartilage oligomeric matrix protein (COMP) which is an important noncollagenous component of cartilage and may play a key role in osteoarthritis pathogenesis." (PMID 25653475, 2015).
pseudoachondroplasia (68 papers, 2005 to 2026). Pseudoachondroplasia is characterized by severe growth deficiency and deformations such as bow legs and hyperlordosis. "Some COMP mutations previously identified in pseudoachondroplasia, an allelic disorder of MED1, were shown in our study to exhibit a typical MED1 or intermediate phenotype." (PMID 42074581, 2026). "Mutations in COMP cause pseudoachondroplasia, a severe dwarfing condition associated with premature joint degeneration and significant lifelong joint pain and less severe multiple epiphyseal dysplasia." (PMID 41009743, 2025). "A novel mutation in exon 18 of COMP in the C-terminal globular domain has been identified as one producing a severe pseudoachondroplasia phenotype with marked short stature, spinal deformities and deformed skeletal appendages." (PMID 41009743, 2025). "Over 40 frame insertion/deletion mutations in the COMP gene cause the skeletal dysplasias, pseudoachondroplasia and less severe multiple epiphyseal dysplasia." (PMID 41009743, 2025). "Significant efforts have been devoted to identifying how mutations in COMP lead to the phenotypic manifestations of pseudoachondroplasia (PSACH), a well-characterized dwarfing condition." (PMID 39795874, 2024). "The sequencing of the COMP gene revealed a previously reported, pathogenic heterozygous variant that is responsible for the development of the pseudoachondroplasia phenotype." (PMID 36890482, 2023). "Some studies describe combinations of DMD caused by deletions in the DMD gene with skeletal dysplasia: osteogenesis imperfecta (mutations in the COL1A1 gene) and pseudoachondroplasia (mutation in the COMP gene)." (PMID 37569734, 2023). "Pseudoachondroplasia arises from a pathogenic variant in Cartilage Oligomeric Matrix Protein (COMP) that ultimately result in epiphyseal dysplasia." (PMID 37675393, 2023). "Here, we present the case of a young female carrying pathogenic NF1 and COMP mutations, diagnosed with two distinct heritable disorders, neurofibromatosis type 1 and pseudoachondroplasia." (PMID 36890482, 2023). "COMP levels are reduced in cartilage diseases such as OA, and mutations in COMP lead to skeletal disorders such as pseudoachondroplasia and multiple epiphyseal dysplasia." (PMID 37469450, 2023). "Gene mutations in COMP are associated with pseudoachondroplasia and multiple epiphyseal dysplasias and COMP is the only thrombospondin that has been associated with skeletal disorders in humans." (PMID 35883515, 2022). "In humans, mutations in the COMP gene lead to pseudoachondroplasia (PSACH) and multiple epiphyseal dysplasia (MED)." (PMID 36452329, 2022). "She benefited from an opinion from geneticists who eliminated the diagnosis of pseudoachondroplasia, known to be associated with COMP mutation." (PMID 34680093, 2021). "Accordingly, mutations in the COMP gene can lead to pseudoachondroplasia and multiple epiphyseal dysplasia." (PMID 31737569, 2019). "Pseudoachondroplasia (PSACH) is an autosomal dominant osteochondrodysplasia caused by mutations in the gene encoding cartilage oligomeric matrix protein (COMP)." (PMID 29104872, 2017). "Mutations in COMP are associated with pseudoachondroplasia (OMIM177170) and multiple epiphyseal dysplasia (OMIM132400)." (PMID 24498183, 2014). "COMP mutations have been described as the cause of pseudoachondroplasia (PSACH) and multiple epiphyseal dysplasia (MED)." (PMID 24376648, 2013). "Mutations in COMP cause human pseudoachondroplasia (PSACH; MIM#177170) and multiple epiphyseal dysplasia (EDM1; MIM#132400), diseases of short stature and osteoarthiritis, both of which are associated with retention of mutant COMP within the rER." (PMID 24348270, 2013). "Pseudoachondroplasia (PSACH) results from mutations in cartilage oligomeric matrix protein (COMP) and the p.D469del mutation within the type III repeats of COMP accounts for approximately 30% of PSACH." (PMID 22006726, 2012).
pseudoachondroplasia (continued). "Pseudoachondroplasia (PSACH) is caused exclusively by mutations in the gene for cartilage oligomeric matrix protein (COMP)." (PMID 21599986, 2011). "Mutations of COMP are related to specific diseases, such as pseudoachondroplasia and multiple epiphyseal dysplasia." (PMID 21935359, 2011). "Mutations in cartilage oligomeric matrix protein (COMP), a large extracellular glycoprotein expressed in musculoskeletal tissues, cause two skeletal dysplasias, pseudoachondroplasia and multiple epiphyseal dysplasia." (PMID 20421976, 2010). "The importance of COMP for cartilage structure and function is underscored further by the findings that COMP mutations cause human skeletal dysplasia, pseudoachondroplasia (PSACH), and multiple epiphyseal dysplasia (MED)." (PMID 19014566, 2008). "Disruptions or mutations in the COMP structure have been linked with skeletal development disorders such as pseudoachondroplasia and multiple epiphyseal dysplasia, underlining the importance of COMP in the tissue." (PMID 17854486, 2007). "Indeed, under physiological conditions COMP plays a crucial role in the organization of cartilage and bone development supported by the fact that mutations in COMP are associated with pseudoachondroplasia and multiple epiphyseal dysplasia." (PMID 31737569, 2019). "It has been shown earlier for mutations in COMP that both intra- and extra-cellular pathways are involved in the pathogenesis of pseudoachondroplasia and that disruption of the ECM structure may cause phenotypes even in the absence of impaired secretion." (PMID 29439465, 2018). "Furthermore, pseudoachondroplasia knock-in mice carrying the COMP p.Thr583Met mutation that causes a skeletal phenotype in humans exhibited short-limb dwarfism and severe degeneration of articular cartilage." (PMID 29262782, 2017). "Some authors have also proposed that caspase-independent necroptosis could be induced by pseudoachondroplasia-linked mutation of COMP (D469del-COMP) in chondrocytes." (PMID 27999417, 2016). "Up to now, COMP is the only gene known to be associated with pseudoachondroplasia." (PMID 21599986, 2011). "This case report details the successful use of over-the-counter resveratrol and CurQ+ in a five-year-old with pseudoachondroplasia (PSACH), a severe dwarfing condition caused by mutations in cartilage oligomeric matrix protein (COMP)." (PMID 40291262, 2025). "Widespread mutations in COMP (COMPopathies) cause ER stress and result in chondrocyte apoptosis and diseases where the skeleton is distorted in pseudoachondroplasia (PSACH) and multiple epiphyseal dysplasia (MED)." (PMID 41009743, 2025). "Mutations in COMP lead to two different, but clinically related, rare skeletal dysplasias: pseudoachondroplasia (PSACH) and multiple epiphyseal dysplasia (MED)." (PMID 41465495, 2025). "Pseudoachondroplasia (PSACH), a severe dwarfing condition associated with early-onset joint degeneration and lifelong joint pain, is caused by mutations in cartilage oligomeric matrix protein (COMP)." (PMID 37892235, 2023). "Mutations in cartilage oligomeric matrix protein (COMP) causes protein misfolding and accumulation in chondrocytes that compromises skeletal growth and joint health in pseudoachondroplasia (PSACH), a severe dwarfing condition." (PMID 36835255, 2023). "In contrast, mutations in COMP cause pseudoachondroplasia (PSACH), a severe dwarfing condition characterized by disproportionately short stature, short limbs, joint laxity, pain, and early-onset joint degeneration." (PMID 37892235, 2023). "Mutations in COMP cause pseudoachondroplasia (PSACH), a severe dwarfing condition characterized by disproportionate short stature, short limbs, joint laxity, pain, and early onset joint degeneration." (PMID 34502142, 2021). "Mutations in the cartilage oligomeric matrix protein (COMP) gene cause both pseudoachondroplasia (PSACH) and multiple epiphyseal dysplasia (MED)." (PMID 29899997, 2018).